HDAC6 (histone deacetylase 6)
Diseases named in the same sentence as HDAC6 in open-access papers (continued):
Sharing a sentence is not in itself a finding about the gene and the disease.
autoimmune disease (7 papers, 2017 to 2022). A disorder resulting from loss of function or tissue destruction of an organ or multiple organs, arising from humoral or cellular immune responses of the individual to their own tissue constituents. "Since IL-17 production is associated with autoimmunity, these observations implicate a protective role for HDAC6 in the development of autoimmune disease via inhibition of Th17 cell differentiation." (PMID 30792714, 2019). "HDAC6 inhibition has shown efficiency in multiple preclinical models of inflammatory and autoimmune diseases, including IBD, RA, systemic lupus erythematosus (SLE), multiple sclerosis, lung inflammatory diseases, allograft rejection, skin inflammatory diseases, sepsis, and acute liver injury." (PMID 33922725, 2021). "Furthermore, HDAC6 inhibitors have also been tested in solid organ malignancies, autoimmune diseases, and neurodegenerative diseases." (PMID 32676030, 2020). "Additionally, one study suggests that inhibition of HDAC6 with a selective HDAC6 inhibitor, such as tubastatin A, alleviates several inflammatory and autoimmune diseases." (PMID 32221047, 2020). "Hence, to date, HDAC6 targeting appears to be the best option for pharmacologic enhancement of Treg function, with potential utility in the management of patients undergoing organ transplantation or in patients suffering from autoimmune diseases." (PMID 28819166, 2017). "Other studies have confirmed that HDAC6 is involved in cell migration, immune synapse formation, and intercellular interactions, and HDAC6 overexpression leads to immune synapse disorders, suggesting that it may be related to the development of autoimmune diseases." (PMID 35449808, 2022). "The two members of class IIb HDACs; HDAC6, and HDAC10 have both been assessed for their therapeutic potential as a new treatment of autoimmune disease." (PMID 30792714, 2019). "Multiple HDAC6-selective inhibitors are in clinical development for indications such as cancer, neurodegeneration, and autoimmune diseases and, to our knowledge, have not elicited adverse effects in humans." (PMID 35575093, 2022). "Although there are no human clinical studies as yet in inflammatory and autoimmune disease patients, similarly to class I HDACi in patients with cancer, HDAC6 inhibitors exhibit an improved safety profile compared with pan-HDACi." (PMID 33922725, 2021).
heart failure (7 papers, 2017 to 2025). Inability of the heart to pump blood at an adequate rate to meet tissue metabolic requirements. "Here, we show that inhibiting HDAC6 with TYA-018 effectively reverses established heart failure and its associated symptoms in male HFpEF mouse models." (PMID 38409164, 2024). "We have previously published data showing that targeted inhibition of histone deacetylase 6 can augment contractility of myofibrils to normalize whole heart function in an angiotensin model of rodent heart failure." (PMID 30838216, 2019). "While Dap may improve AR by alleviating post‐MI heart failure, our findings suggest that its protective effects are at least partly attributable to direct inhibition of HDAC6." (PMID 40377174, 2025). "Furthermore, a study using a mouse model of dilated cardiomyopathy highlighted the cardioprotective efficacy of HDAC6 inhibitors, suggesting their potential as a therapeutic approach for cardiomyopathy and various forms of heart failure." (PMID 40520229, 2025). "A recent study has reported that a microbiota-derived tryptophan metabolite, indole-3-propionic acid, is beneficial in heart failure by reducing oxidative stress, cardiomyocyte death and inflammation via inhibition of histone deacetylase 6/NADPH oxidase 2 (HDAC6/NOX2) signaling." (PMID 37626809, 2023). "Our data showed that GGD inhibited HDAC6 and increased tubulin acetylation, which may have beneficial effects on heart failure." (PMID 28798797, 2017).
rheumatoid arthritis (7 papers, 2016 to 2024). A chronic, systemic autoimmune disorder characterized by inflammation in the synovial membranes and articular surfaces. "We used rheumatoid arthritis fibroblast-like synoviocytes (RA-FLS) and collagen-induced arthritis mice (CIA mice) as models of RA and pharmacological inhibitors as well as genetic interference with adeno-associated viruses to reduce the expression of HDAC6." (PMID 38576491, 2024). "In summary, these results indicate that the downregulation of HDAC6 can alleviate rheumatoid arthritis." (PMID 38576491, 2024). "Activates p38 and Akt pathways and increase expression of HDAC6 by more than 200% in rheumatoid arthritis synovial fibroblasts.Increases HDAC6 expression, which led to enhancement of the detrimental effects of TNF-α in RA synovial fibroblasts." (PMID 32397127, 2020). "Therefore, inhibiting the expression of HDAC6 can effectively ameliorate synovial inflammation in rheumatoid arthritis patients." (PMID 38576491, 2024). "Overall, we conclude that the inhibition of HDAC6 can downregulate CMA and thereby ameliorate rheumatoid arthritis HDAC6 may be a new potential target for the clinical treatment of rheumatoid arthritis." (PMID 38576491, 2024). "We investigated the therapeutic effect of a new selective HDAC6 inhibitor, CKD-L, compared to ITF 2357 or Tubastatin A on CIA and regulatory T (Treg) cells in patients with rheumatoid arthritis (RA)." (PMID 28673326, 2017).
systemic lupus erythematosus (7 papers, 2017 to 2024). An autoimmune multi-organ disease typically associated with vasculopathy and autoantibody production. "It should be noted, however, that HDAC6 inhibitors can also be used for the treatment of systemic lupus erythematosus, a B cell-associated immune system disease, by correcting abnormal cell metabolism and reducing the inflammatory environment." (PMID 32676030, 2020). "In a previous study, we found that the expression of HDAC6 and its activity was significantly increased in B cells from lupus prone mice compared to healthy control mice, suggesting the pathogenic role of HDAC6 in lupus." (PMID 31708928, 2019). "Furthermore, HDAC6 inhibitors have been shown to suppress various signaling pathways associated with B-cell activation and differentiation, thereby inhibiting the formation of plasma cells and germinal center (GC) response in lupus model mice." (PMID 39606248, 2024). "One month after lupus model mice were treated with a selective HDAC6 inhibitor, lupus nephritis (LN) symptoms were significantly alleviated, and the deposition of IgG and C3 in glomeruli was significantly decreased." (PMID 39606248, 2024). "We have previously shown that the selective HDAC6 inhibitor ACY-738 given to pre-disease lupus-prone NZB/W mice prevented the onset of lupus nephritis (LN)." (PMID 31708928, 2019). "Specifically, we compared the pathways down-regulated by HDAC6 inhibition in NZB/W mice to pathways up-regulated in human lupus affected organs, including skin, synovium and kidney." (PMID 31708928, 2019). "Of importance, our data also suggests that HDAC6 inhibition corrects aberrant cellular metabolism observed in lupus." (PMID 31708928, 2019). "In order to demonstrate the relevance of our findings regarding HDAC6 inhibitor-mediated suppression of molecular pathways in lupus mice, we compared the downregulated pathways to those found to be up-regulated in active human lupus." (PMID 31708928, 2019). "Finally, when RNA profiles from the NZB/W mice were compared to humans with lupus, our results demonstrate that the many of genes upregulated in lupus patients were decreased lupus mice with HDAC6 inhibition." (PMID 31708928, 2019). "In addition, we sought to bridge between the transcriptomic data obtained from the HDAC6 treated mice and human gene expression information to determine the relevance to this target in possibly controlling human lupus." (PMID 31708928, 2019). "Moreover, the molecular pathways suppressed by the HDAC6 inhibitor were frequently overexpressed in human lupus tissue." (PMID 31708928, 2019). "The current studies confirm that HDAC6 inhibition decreased the Tfh population in lupus mice." (PMID 31708928, 2019). "In addition to HDAC6 inhibiting B cell and T cell activation, several metabolic and enzymes pathways that are known to be increased in active lupus were also ameliorated." (PMID 31708928, 2019). "For example, pharmacological inhibition of HDAC6 in a preclinical model of systemic lupus erythematosus (SLE) reduced infiltrating T follicular helper (TFH) cells into germinal centers (GCs) with significant consequences on autoantibody titers." (PMID 37485352, 2023). "When we compared the HDAC6 inhibitor treated lupus mouse gene signatures to human lupus patient gene signatures, the results showed numerous immune and inflammatory pathways increased in active human lupus affected tissue were significantly decreased in the HDAC6 inhibitor treated animals." (PMID 31708928, 2019). "Pathway analysis suggested alterations in cellular metabolism might contribute to the normalization of lupus mouse spleen genomic signatures, and this was confirmed by direct measurement of the impact of the HDAC6 inhibitor on metabolic activities of murine spleen cells." (PMID 31708928, 2019). "In lupus, HDAC6 may act to regulate both innate and adaptive immune responses." (PMID 31708928, 2019).
systemic lupus erythematosus (continued). "When the HDAC6 inhibitor-treated lupus mouse gene signatures were compared to human lupus patient gene signatures, the results showed numerous immune, and inflammatory pathways increased in active human lupus were significantly decreased in the HDAC6 inhibitor treated animals." (PMID 31708928, 2019). "To simulate the therapeutic paradigm in human lupus, we treated 20-week-old NZB/W F1 female (NZB/W) mice with established LN with the selective HDAC6 inhibitor ACY-738." (PMID 31708928, 2019). "Our rationale for continued investigations to define the molecular events in lupus immunopathogenesis mediated by HDAC6 is related to the uncertainty of the non-redundant roles of HDAC6 in immune function in general and lupus in particular." (PMID 31708928, 2019). "Different from lupus-prone mice, the lack of HDAC6 in mice of B6 background showed no reduction of splenic spontaneous germinal centers in steady state." (PMID 31708928, 2019).
acute liver failure (6 papers, 2019 to 2025). Rapid deterioration of liver function causing encephalopathy and coagulopathy. "HDAC6 regulates the activation of M1 macrophages by downregulating NLRP3 expression during acute liver failure." (PMID 35910382, 2022). "For example, inhibition of HDAC6 protects against acute liver failure by activating AMPK signaling pathway." (PMID 33456556, 2021). "In contrast, HDAC6—a cytoplasmic class IIb deacetylase—has been shown to suppress ferroptosis, but in the context of acute liver failure rather than cancer." (PMID 40947430, 2025).
amyloid (6 papers, 2013 to 2024). "When APPPS1-21 mice, which show memory impairment, amyloid pathology and low levels of α-tubulin acetylation, were crossed with Hdac6 knockout mice, it was found that the reduction in HDAC6 led to improvement in memory function, accompanied by robust increases in acetylated α-tubulin." (PMID 30935091, 2019). "However, when crossed with a model for severe amyloid pathology, reduction of HDAC6 levels ameliorated the impairment of α-tubulin K40ac and associative and spatial memory formation." (PMID 23184605, 2013). "Finally, the positive impact of HDAC6 depletion in cognition has been recently demonstrated by crossing HDAC6 knockdown mice with a model for severe amyloid pathology." (PMID 23356410, 2013). "A heterologous distribution of HDAC6-specific radioligand [18F]PB118 was found with the most pronounced changes in the cerebral cortex and hippocampus similar to the distribution of amyloid deposits." (PMID 37298694, 2023).
B-cell lymphoma (6 papers, 2018 to 2023). "It was shown that HDAC6 inhibition by compound 34 led to hyperacetylation of tubulin followed by enhanced binding of DNAJA3 to hyperacetylated tubulin in the cytoplasm of B-cell lymphoma cells, which led to enhanced Myc degradation." (PMID 36835501, 2023). "Taken together, our data demonstrate a beneficial role of HDAC6 inhibition in MYC-dependent B-cell lymphoma." (PMID 36068335, 2022). "Previous strategies to inhibit HDAC6 using ACY-1215 in B-cell lymphoma resulted in an activation of the unfolded protein response by increasing quantity and acetylation of HSPs." (PMID 36068335, 2022). "Selective inhibition of cytoplasmic HDAC6 by the HDAC6 inhibitor 34 (marbostat) led to MYC degradation and apoptosis in MYC-overexpressing B-cell lymphoma cells." (PMID 36835501, 2023). "Here, we show that inhibition of the histone deacetylase 6 (HDAC6) using the HDAC6 inhibitor Marbostat-100 (M-100) reduces oncogenic MYC levels and prevents lymphomagenesis in a mouse model of MYC-induced aggressive B-cell lymphoma." (PMID 36068335, 2022).
brain tumors (6 papers, 2017 to 2024). "Thus, there is a strong rationale for introducing HDAC6 inhibitors as adjunct therapies for malignant brain tumors, warranting in-depth analyses on the mechanisms by which HDAC6 regulates gliomagenesis." (PMID 33915983, 2021). "In this review article, the available information related to HDAC6 function in GBM will be presented, with the aim of proposing its inhibition as a valuable therapeutic route for this deadly brain tumour." (PMID 39595195, 2024).
cardiomyopathy (6 papers, 2017 to 2025). A disease of the heart muscle or myocardium proper. "Access to such HDAC6 inhibitor would enable us to study the effects of HDAC6 inhibition in cardiomyopathy caused by mutations in LMNA in preclinical in vivo models for translation to clinical trials." (PMID 36550158, 2022). "Building upon our previous research that demonstrates the efficacy of histone deacetylase 6 (HDAC6) inhibition in a genetic cardiomyopathy model, we investigate HDAC6’s role in HFpEF due to their shared mechanisms of inflammation and metabolism." (PMID 38409164, 2024). "Given the shared underlying mechanisms involving inflammation and metabolism in both cardiomyopathy and HFpEF, we were driven to explore the potential role of HDAC6 in HFpEF." (PMID 38409164, 2024). "In fact, Hdac6 has already been identified as a molecular target in a cardiomyopathy mouse model based on the accumulation of misfolded proteins." (PMID 28662206, 2017). "Hence, the finding that α-tubulin acetylation in the heart is involved in cardiomyopathy, and that specific inhibition of HDAC6 has beneficial effects, opens up new therapeutic possibilities." (PMID 36550158, 2022). "Inhibition of HDAC6 activity increases tubulin acetylation and protects against cardiomyopathy." (PMID 28798797, 2017). "Given that HDAC6 inhibitors have lower adverse effects than pan-HDAC inhibitors, such compounds may be important in the array of therapeutic approaches for cardiomyopathy." (PMID 36550158, 2022). "siRNA mediated knockdown of HDAC6 or non-selective HDAC inhibition induces tubulin hyper-acetylation, which was accompanied by aggregate formation in cardiomyopathy mice hearts." (PMID 30081552, 2018).
chronic lymphocytic leukemia (6 papers, 2018 to 2025). "However, in cutaneous T-cell lymphoma and chronic lymphocytic leukemia, HDAC6 overexpression is correlated with longer survival." (PMID 30050135, 2018). "In bladder urothelial carcinoma and chronic lymphocytic leukemia (CLL) cell lines, selective HDAC6 blockade prompted PD-L1 upregulation." (PMID 38672128, 2024).
colitis (6 papers, 2021 to 2023). Inflammation of the colon. "Another inhibitor of HDAC6 also exhibited protective effects on colitis in mice by preventing NLRP3 inflammasome activation." (PMID 38155235, 2023). "In this study, we have shown that WT161, an inhibitor of HDAC6, exerts a protective role in a colitis model, blocks NLRP3 inflammasome activation, disrupts ASC speck formation, and decreases the expression of NLRP3." (PMID 35330829, 2022). "In this study, we found that the HDAC6 inhibitor WT161 exerts a protective effect in a DSS-induced colitis murine model and blocks NLRP3 inflammasome activation, as IL-1β release and ASC oligomerization were inhibited in the WT161-treated group." (PMID 35330829, 2022). "HDAC6 is a member of the histone deacetylase family proposed as anti-inflammatory therapy for treating colon inflammation that may progress to IBD." (PMID 34838026, 2021). "The inhibitor of HDAC6 could restrain B-cell infiltration in DSS-induced colitis in mice." (PMID 38155235, 2023). "In previous studies, selective HDAC6 inhibition was found to suppress the secretion of key inflammatory cytokines and chemokines in DSS-induced colitis." (PMID 36558966, 2022). "Based on these studies, we suspect that the HDAC6 inhibitor WT161 can inhibit the activation of NLRP3 inflammasome and alleviate colitis in DSS-treated mice." (PMID 35330829, 2022).
cutaneous T-cell lymphoma (6 papers, 2008 to 2024). "The study conducted by Marquard and collaborators in cutaneous T-cell lymphoma (CTCL) patients reported a high expression level of HDAC1, HDAC2, and HDAC6, and an association between the levels of HDAC2 and histone H4 acetylation and tumor aggressiveness." (PMID 30096875, 2018). "SAHA has been approved for treating cutaneous T-cell lymphoma and is identified as a pan-inhibitor for class I and class II HDACs (including HDACs 1, 2, 3, and 6), while tubacin is a HDAC6-selective inhibitor." (PMID 26517515, 2015). "Expression of HDAC1, HDAC2, HDAC6, and acetylated H4 (H4ace) in different subtypes of cutaneous T-cell lymphoma (CTCL) (n = 73)." (PMID 18671804, 2008). "In cutaneous T-cell lymphoma, upregulation of HDAC1 and HDAC6 was detected as a result of excessive autocrine production of IL-15 driven by disruption of the Zeb1 transcription factor binding to the IL-15 promoter." (PMID 35887172, 2022).
head and neck squamous cell carcinoma (6 papers, 2018 to 2021). A squamous cell carcinoma that arises from any of the following anatomic sites: lip and oral cavity, nasal cavity, paranasal sinuses, pharynx, larynx, and salivary glands. "It was reported that miR-206 is involved in the progression of human head and neck squamous cell carcinoma by mediating HDAC6 through PTEN/AKT/mTOR pathway." (PMID 32833118, 2021). "Meanwhile, it was revealed that in head and neck squamous cell carcinoma, inhibition of mTOR/Akt pathway signalling inhibits HDAC6." (PMID 33547375, 2021). "Liu et al47 showed that miR‐206 suppressed head and neck squamous cell carcinoma cell growth, invasion and migration through targeting HDAC6 via mTOR/PTEN/AKT pathway." (PMID 30156374, 2018).